KCNA6 (potassium voltage-gated channel subfamily A member 6)
Description:
Voltage-gated potassium channel that mediates transmembrane potassium transport in excitable membranes. Forms tetrameric potassium-selective channels through which potassium ions pass in accordance with their electrochemical gradient. The channel alternates between opened and closed conformations in response to the voltage difference across the membrane. Can form functional homotetrameric channels and heterotetrameric channels that contain variable proportions of KCNA1, KCNA2, KCNA4, KCNA6, and possibly other family members as well; channel properties depend on the type of alpha subunits that are part of the channel (By similarity). Channel properties are modulated by cytoplasmic beta subunits that regulate the subcellular location of the alpha subunits and promote rapid inactivation (By similarity). Homotetrameric channels display rapid activation and slow inactivation.
Synonyms: Kv1.6; HBK2; PPP1R96
Tractability: Small molecule: an approved drug acts on it; it belongs to a druggable protein family. Antibody: UniProt places it where antibodies can reach, with high confidence; its Gene Ontology location is reachable by antibodies, with high confidence; UniProt predicts a signal peptide or a membrane-spanning region. PROTAC: its protein half-life has been measured; a small molecule that binds it is known.
Target class: Potassium channels; Ion channel; Voltage-gated ion channel; Voltage-gated potassium channel
Gene: Protein-coding gene on chromosome 12 (4,809,334 to 4,813,318, forward strand). Ensembl gene ENSG00000151079.
Subcellular location: Cell membrane
Subcellular location (Human Protein Atlas): Cytosol; Plasma membrane; Vesicles
Pathways (Reactome):
Neuronal System: Voltage gated Potassium channels
Gene Ontology:
Molecular function: delayed rectifier potassium channel activity; protein binding; voltage-gated potassium channel activity; monoatomic ion channel activity
Biological process: potassium ion transmembrane transport; action potential; potassium ion transport; monoatomic ion transport; protein homooligomerization; transmembrane transport
Cellular component: plasma membrane; membrane; potassium channel complex; voltage-gated potassium channel complex; axon; axon terminus
Genetic constraint (gnomAD): Loss-of-function variants: 19 observed, 32.76 expected, observed/expected ratio (o/e) 0.58, 90% interval 0.4 to 0.85. The upper end of that interval is the gene's LOEUF score, 0.85, which puts it in group 3 of 6, group 1 being the genes least tolerant of losing a copy. Missense variants: 450 observed, 727.46 expected, observed/expected ratio (o/e) 0.62, 90% interval 0.57 to 0.67. Synonymous variants: 296 observed, 312.87 expected, observed/expected ratio (o/e) 0.95, 90% interval 0.86 to 1.04.
Homologues: Orthologues: chimpanzee KCNA6 (99% identical), macaque KCNA6 (99% identical), pig KCNA6 (96% identical), rabbit KCNA6 (96% identical), dog KCNA6 (95% identical), mouse Kcna6 (93% identical), rat Kcna6 (93% identical), guinea pig KCNA6 (88% identical). Paralogues in human: KCNA3 (65% identical), KCNA2 (64% identical), KCNA1 (61% identical), KCNA4 (61% identical), KCNA5 (61% identical), KCNA7 (57% identical), KCNA10 (55% identical), KCNC3 (34% identical), KCNC2 (34% identical), KCNC4 (33% identical), KCNC1 (33% identical), KCNB2 (32% identical), and 19 more.
Diseases named in the same sentence as KCNA6 in open-access papers:
KCNA6 is named in the same sentence as 24 diseases in open-access papers, as found by Europe PMC text mining. Sharing a sentence is not in itself a finding about the gene and the disease. The quoted sentences say what the papers report.
COVID-19 (2 papers, 2023 to 2025). A disease caused by infection with severe acute respiratory syndrome coronavirus 2. "In addition, Kcna6 may be used as a target for treating COVID-19 since it can facilitate the entry of SARS-CoV-2 into neurons." (PMID 38005876, 2023).
epilepsy (2 papers, 2017 to 2023). A brain disorder characterized by episodes of abnormally increased neuronal discharge resulting in transient episodes of sensory or motor neurological dysfunction, or psychic dysfunction. "Even though our cohort is small, it establishes KCNA6 as a gene associated with neurodevelopmental disorders and epilepsy." (PMID 36318112, 2023). "KV channel blockers may thus be of therapeutic interest for individuals affected with KCNA6‐related epilepsy with associated gain‐of‐function mechanisms." (PMID 36318112, 2023). "KCNA6 mRNA and KV1.6 expression were increased in the piriform cortex parvalbumin interneurons following induction of epilepsy, demonstrating KV1.6 expression in inhibitory interneurons." (PMID 36318112, 2023).
neuroma (2 papers, 2016 to 2021). A tumor that grows from a nerve or is composed of nerve cells and nerve fibers. "Upregulation of Kcna6 in painful rat and human neuromas has implicated this subunit in a compensatory response to nerve injury." (PMID 34544832, 2021).
acute lymphoblastic leukemia (1 paper, 2025). Leukemia with an acute onset, characterized by the presence of lymphoblasts in the bone marrow and the peripheral blood. "We selected the T-cell acute lymphoblastic leukemia cell line Loucy as it expresses moderate levels of endogenous KCNA6 and LGMN, low levels of TMPRSS2, and low to undetectable levels of ACE2." (PMID 40674406, 2025).
Arrhythmia (1 paper, 2015). Any cardiac rhythm other than the normal sinus rhythm. "Moreover, calcium handling and contractile function genes (SLN, ACTC1, PLCD4, PLCZ), potential arrhythmia-related genes (MYO5B, KCNA5), and cytoskeleton and cellular organization-related genes (XIRP2, COL8A1, KCNA6) were among the most deregulated genes in rTOF ventricles." (PMID 26252659, 2015).
Ataxia (1 paper, 2023). Ataxia refers to impaired coordination of voluntary muscle movement. "None of the affected individuals carrying KCNA6 de novo variants exhibited ataxia or cerebellar involvement, which are frequent features in the neurological and neuroradiological phenotypes related to genetic defects in KV1.116, 17, 18, 22 and KV1.2 channels." (PMID 36318112, 2023).
autism spectrum disorder (1 paper, 2021). A spectrum of developmental disorders that includes autism, and Asperger syndrome. "It is interesting to note that an increase in the expression of the KCNA6 gene (which has a similar function) was previously observed in another autism spectrum disorder (ASD) model and in RNA extracted from the hippocampi of IQSEC2 model mice (data not shown)." (PMID 34535765, 2021).
channelopathy (1 paper, 2023). Channelopathies are a group of diseases caused by the dysfunction of ion channel subunits or their interacting proteins. "Our data highlight KCNA6 as a novel channelopathy gene associated with early infantile epileptic phenotypes and neurodevelopmental anomalies." (PMID 36318112, 2023).
Morton Neuroma (1 paper, 2025). Swelling and inflammation of the nerve between the ends of the metatarsal bones at the base of the toes. "When we talk about Kcna6, its increased expression has been reported in sciatic nerve injury and has been associated with neuropathic pain and Morton’s neuroma." (PMID 41155561, 2025).
virus infection (1 paper, 2025). "We found that loss of KCNA6 or LGMN significantly decreased viral infection by replication competent SARS-CoV-2." (PMID 40674406, 2025). "In orthogonal experiments, we show that disruption of endogenous LGMN or KCNA6 decreases viral infection and that inhibitors of candidate factors can reduce viral entry." (PMID 40674406, 2025). "In a complementary assay using replicating Spike-pseudotyped VSV with time-lapse imaging of virus infection, we found that two of the strongest hits validated by the pseudotyped lentiviral experiments, KCNA6 and LGMN, were able to similarly promote infection." (PMID 40674406, 2025). "Using a monoclonal 293T cell line with ACE2 genetically disrupted (hereafter ACE2KO 293T), we found that overexpression of ACE2 could induce viral infection, but overexpression of either KCNA6 or LGMN in this context did not promote entry by SARS-CoV-2 live virus over background levels." (PMID 40674406, 2025).
cancer (3 papers, 2022 to 2025). A tumor composed of atypical neoplastic, often pleomorphic cells that invade other tissues. "We evaluated the overall genetic alterations in all KCNA genes (KCNA1, KCNA2, KCNA3, KCNA4, KCNA5, KCNA6, KCNA7, KCNA10) using the TCGA Pan-Cancer Atlas dataset, collecting data from 32 human cancers (10,953 patients in total)." (PMID 36978819, 2023). "For the remaining gDMs (NPY, FOXE1, FAIM2, and KCNA6), we found hyper-methylation in PDAC, as confirmed by the higher extent of methylation in cancer samples." (PMID 36329447, 2022).
neurodevelopmental disorder (2 papers, 2023 to 2024). A behavioral and cognitive disorder with onset during the developmental period that involves impaired or aberrant development of intellectual, motor, or social functions. "We identified four KCNA6 variants in patients with varying degrees of neurodevelopmental disorder and seizures." (PMID 36318112, 2023). "We identified novel de novo variants in KCNA6 in four unrelated individuals variably affected with neurodevelopmental disorders and seizures with onset in the first year of life." (PMID 36318112, 2023).
infection (1 paper, 2025). The state of being infected such as from the introduction of a foreign agent such as serum, vaccine, antigenic substance or organism. "Additionally, we found that KCNA6 maintained its ability to confer increased infection when using either B.1.351 (Beta) or B.1.617 (Delta) Spike-pseudotyped lentiviruses." (PMID 40674406, 2025). "It is important to note that our data does not provide evidence that KCNA6 functions through a direct interaction with the Spike protein, and it remains to be tested whether KCNA6 expression promotes infection through protein-protein interactions or an indirect effect on cell physiology." (PMID 40674406, 2025). "We transduced the cells with lentiCRISPRv2 constructs targeting either ACE2, TMPRSS2, KCNA6, or LGMN and subjected the knock-out cell lines to infection with replication competent SARS-CoV-2." (PMID 40674406, 2025). "Treatment of KCNA6 expressing Loucy cells with 3,4-DAP lead to a reduction, but not complete ablation, in infection by lentiviruses pseudotyped with D614G Spike." (PMID 40674406, 2025).
neurological disorders (1 paper, 2023). "Low tolerance of KCNA6 for missense variation suggests that further variants, including loss‐of‐function variants are likely to be discovered associated with neurological disorders." (PMID 36318112, 2023). "Our functional data implicate defective deactivation (gain‐of‐function) as a pathogenic mechanism for KCNA6‐related neurological disorders." (PMID 36318112, 2023).
KCNA6 also shares sentences with these, for which no sentence is quoted: injury (2 papers); Epileptic encephalopathy (1); Fabry disease (1); gastric cancer (1); heart failure (1); infantile-onset epilepsy (1); neuropathic pain (1); Parkinson disease (1); small cell lung carcinoma (1); tumor (1).